NEUROD4 (neuronal differentiation 4)
Description:
Probably acts as a transcriptional activator. Mediates neuronal differentiation. Required for the regulation of amacrine cell fate specification in the retina (By similarity).
Synonyms: bHLHa4; ATH-3; Atoh3; ATH3; MATH-3; MATH3
Tractability: PROTAC: ubiquitination databases record sites on it.
Gene: Protein-coding gene on chromosome 12 (55,019,974 to 55,030,017, forward strand). Ensembl gene ENSG00000123307.
Subcellular location: Nucleus
Subcellular location (Human Protein Atlas): Nucleoplasm; Centrosome; Cytosol
Gene Ontology:
Molecular function: protein binding; DNA-binding transcription factor activity, RNA polymerase II-specific; E-box binding; protein dimerization activity
Biological process: amacrine cell differentiation; axon development; camera-type eye development; positive regulation of cell differentiation; positive regulation of transcription by RNA polymerase II; nervous system development; regulation of DNA-templated transcription
Cellular component: centrosome; cytosol; nucleoplasm; chromatin; nucleus
Genetic constraint (gnomAD): Loss-of-function variants: 16 observed, 20.4 expected, observed/expected ratio (o/e) 0.78, 90% interval 0.53 to 1.19. The upper end of that interval is the gene's LOEUF score, 1.19, which puts it in group 5 of 6, group 1 being the genes least tolerant of losing a copy. Missense variants: 439 observed, 418.63 expected, observed/expected ratio (o/e) 1.05, 90% interval 0.97 to 1.13. Synonymous variants: 153 observed, 156.26 expected, observed/expected ratio (o/e) 0.98, 90% interval 0.86 to 1.12.
Homologues: Orthologues: chimpanzee NEUROD4 (99% identical), macaque NEUROD4 (98% identical), pig NEUROD4 (92% identical), rabbit NEUROD4 (91% identical), guinea pig NEUROD4 (91% identical), mouse Neurod4 (89% identical), rat Neurod4 (87% identical), tropical clawed frog neurod4 (65% identical), zebrafish neurod4 (59% identical), Drosophila melanogaster tap (19% identical), Caenorhabditis elegans ngn-1 (18% identical), Drosophila melanogaster ato (12% identical), and 2 more. Paralogues in human: NEUROD1 (53% identical), NEUROD2 (43% identical), NEUROD6 (43% identical), NEUROG2 (22% identical), NEUROG1 (20% identical), ATOH1 (19% identical), OLIG2 (19% identical), OLIG3 (19% identical), NEUROG3 (18% identical), BHLHA15 (17% identical), BHLHE22 (16% identical), BHLHE23 (16% identical), and 3 more.
Diseases named in the same sentence as NEUROD4 in open-access papers:
NEUROD4 is named in the same sentence as 10 diseases in open-access papers, as found by Europe PMC text mining. Sharing a sentence is not in itself a finding about the gene and the disease. The quoted sentences say what the papers report.
glioblastoma (2 papers, 2022 to 2023). The most malignant astrocytic tumor (WHO grade IV). "To summarize, our study demonstrates that NeuroD4 overexpression can reprogram glioblastoma cells into neuron-like cells through the SLC7A11-GSH-GPX4 signaling pathway, thus offering a potential novel therapeutic approach for glioblastoma." (PMID 37582760, 2023). "The high positive rates of TUJ1 and MAP2 in GFP+ cells of the GFP+NeuroD4 group lead us to conclude that NeuroD4 overexpression efficiently reprograms specific glioblastoma cell types into neuron-like cells." (PMID 37582760, 2023). "We initially investigated the role of NeuroD4 in inducing neuronal reprogramming of human glioblastoma cells." (PMID 37582760, 2023). "Compared to the GFP group, the GFP+NeuroD4 group showed a significant rightward shift in the peak of the PE channel and an increase in fluorescence intensity, indicating the accumulation of ROS in glioblastoma cells following NeuroD4 overexpression." (PMID 37582760, 2023). "In our study, we observed a significant inhibition of proliferation in the successfully reprogrammed malignant glioblastoma cells, aligning with our objective of delaying tumor progression through NeuroD4 overexpression." (PMID 37582760, 2023). "One day after infection with GFP and GFP+NeuroD4 lentivirus, the glioblastoma cell medium was replaced." (PMID 37582760, 2023). "Building upon this knowledge, our aim was to investigate the potential of NeuroD4 overexpression in transforming undifferentiated glioblastoma cells into neuron-like cells, arresting their proliferation both in vivo and in vitro." (PMID 37582760, 2023). "To further elucidate the mechanism by which NeuroD4 overexpression affects glioblastoma cell reprogramming, we isolated total RNA from U251 cells infected with GFP and GFP+NeuroD4 viruses, five days after infection, for sequencing." (PMID 37582760, 2023). "In summary, our study provides insights into the molecular basis of NeuroD4-mediated reprogramming of glioblastoma into neuron-like cells." (PMID 37582760, 2023). "RNA-seq results indicated the involvement of DNA replication, mitotic spindle checkpoint, and cell cycle pathways, further supporting the effective blockade of glioblastoma proliferation by NeuroD4-mediated neuronal reprogramming." (PMID 37582760, 2023). "The ferroptosis inhibitor ferrostatin-1 effectively blocked the NeuroD4-mediated process of neuron reprogramming in glioblastoma." (PMID 37582760, 2023). "In our study, we uncovered the crucial role of ferroptosis in NeuroD4-mediated neuronal reprogramming of glioblastoma." (PMID 37582760, 2023). "To confirm that the cell cycle of GFP+NeuroD4 virus-infected glioblastoma cells was arrested in the early stages of reprogramming, we performed a time-course flow cytometry analysis by labeling the DNA of glioblastoma cells with PI dye." (PMID 37582760, 2023). "Notably, the mRNA expression of GPX4, which provides protection against overoxidation and prevents cells from undergoing ferroptosis, exhibited a significant decrease in NeuroD4-overexpressing glioblastoma cells." (PMID 37582760, 2023). "Furthermore, the ferroptosis inhibitor ferrostatin-1 was found to effectively block the neuron reprogramming process mediated by NeuroD4 in glioblastoma." (PMID 37582760, 2023). "Therefore, we investigated whether NeuroD4-mediated neuronal reprogramming could inhibit the aggressive proliferation of glioblastoma cells." (PMID 37582760, 2023). "To investigate whether SLC7A11 and GPX4 inhibit NeuroD4-mediated neuronal reprogramming in glioblastoma cells, we co-overexpressed SLC7A11 and GPX4 along with NeuroD4." (PMID 37582760, 2023). "In our study, NeuroD4 successfully reprogrammed U251 and KNS89 glioblastoma cell lines into a neural differentiation state, achieving an efficiency of over 90%, which is comparable to the reprogramming efficiency achieved by overexpressing ASCL1 or knocking down PTBP1." (PMID 37582760, 2023).
glioblastoma (continued). "In this study, we discovered that NeuroD4 alone effectively reprogrammed human glioblastoma cells into non-proliferating neuron-like cells." (PMID 37582760, 2023). "A time-course cell counting analysis revealed that the control group infected with GFP-expressing virus continued to exhibit aggressive growth, while the growth of glioblastoma cells infected with the GFP+NeuroD4 virus reached a plateau at 5 dpi, showing no significant development thereafter." (PMID 37582760, 2023). "At 7 dpi, compared to the GFP group, glioblastoma cells with forced expression of GFP+NeuroD4 showed a significant decrease in the number of EdU+ and Ki67+ cells, suggesting that NeuroD4-mediated neuronal reprogramming may induce cell cycle exit in U251 and KNS89 cells." (PMID 37582760, 2023).
diabetes (1 paper, 2025). "MAF BZIP Transcription Factor A (MAFA), Neuronal Differentiation 1 (NEUROD1) and NEUROD4 were significantly downregulated (p < 0.05) in the diabetes cohort, suggesting a disruption in the transcriptional regulation of β-cell identity and function." (PMID 40244011, 2025).
lung carcinoma (1 paper, 2019). "Furthermore, NEUROD4 is found to have a very low difference in expressioncompared to the control group in colon, ovarian, breast and lung cancer types." (PMID 31831960, 2019).
neuroendocrine tumors (1 paper, 2022). "As a neuron differentiation factor, NEUROD4 has been reported overexpressed in neuroendocrine tumors." (PMID 36105089, 2022).
Peri-Implantitis (1 paper, 2021). An inflammatory process with loss of supporting bone in the tissues surrounding functioning DENTAL IMPLANTS. "MiRNA-544a regulates the inflammation in spinal cord injury by inhibiting the expression of NEUROD4 These results provide a good reference for the further study of miR544a in peri-implantitis or periodontitis." (PMID 34922523, 2021).
tumor (3 papers, 2022 to 2025). "For example, ZNF117 controls the differentiation of GSCs towards the oligodendroglial lineage, while NeuroD4 and CP-673451 can trigger differentiation of GSCs into neuron-like cells, as well as reduce proliferation and invasion of tumor cells." (PMID 40191211, 2025). "The results revealed a significant inhibition of GFP+NeuroD4 tumor growth in the brain (n = 5, p < 0.001), leading to a significant prolongation of survival time in the nude mice up to 60 days (n = 10, p < 0.001)." (PMID 37582760, 2023). "To assess the impact of NeuroD4 overexpression on tumor growth in vivo, we selected U87 cells carrying a luciferase reporter gene, known for forming brain masses." (PMID 37582760, 2023). "Additionally, NeuroD4 virus-infected xenografts exhibited smaller tumor sizes compared to the control GFP group, and the survival time of tumor-bearing mice in the GFP+NeuroD4 group was prolonged." (PMID 37582760, 2023).
cancer (2 papers, 2019 to 2020). A tumor composed of atypical neoplastic, often pleomorphic cells that invade other tissues. "Genes that have a very similar expression pattern to the control group and appear as such in 4 out of six cancer types are PATE, NEUROD4 and TRAFD1." (PMID 31831960, 2019). "Genes having similar expression (referred as flexible genes) pattern to thecontrol group in four out of six cancer types are PATE, NEUROD4 and TRAFD1." (PMID 31831960, 2019).
infection (1 paper, 2023). The state of being infected such as from the introduction of a foreign agent such as serum, vaccine, antigenic substance or organism. "RNA sequencing confirmed the overexpression of NeuroD4 mRNA, and western blot analysis confirmed the expression of the Flag-NeuroD4 protein in U251, KNS89, and U87 cells infected with the GFP+NeuroD4 virus at 5 days post infection (dpi)." (PMID 37582760, 2023). "The infection efficiency of the GFP+NeuroD4 group was estimated to be more than 91% in U251 cells and 89% in KNS89 cells, based on the co-expression of GFP and nuclear marker DAPI." (PMID 37582760, 2023).
NEUROD4 also shares sentences with these, for which no sentence is quoted: microphthalmia (1 paper); periodontitis (1).